SLC68A1 (solute carrier family 68 member 1)
Description:
May act as a cation symporter.
Synonyms: C10orf77; MFSD13A; TMEM180; FLJ22529; bA18I14.8
Tractability: Antibody: UniProt places it where antibodies can reach, with high confidence; its Gene Ontology location is reachable by antibodies, with high confidence; UniProt predicts a signal peptide or a membrane-spanning region. PROTAC: ubiquitination databases record sites on it.
Gene: Protein-coding gene on chromosome 10 (102,461,363 to 102,477,046, forward strand). Ensembl gene ENSG00000138111.
Subcellular location: Cell membrane
Subcellular location (Human Protein Atlas): Cytosol; Golgi apparatus
Gene Ontology:
Molecular function: protein binding
Cellular component: plasma membrane
Genetic constraint (gnomAD): Loss-of-function variants: 31 observed, 49.54 expected, observed/expected ratio (o/e) 0.63, 90% interval 0.47 to 0.85. The upper end of that interval is the gene's LOEUF score, 0.85, which puts it in group 3 of 6, group 1 being the genes least tolerant of losing a copy. Missense variants: 596 observed, 688 expected, observed/expected ratio (o/e) 0.87, 90% interval 0.81 to 0.93. Synonymous variants: 290 observed, 316.19 expected, observed/expected ratio (o/e) 0.92, 90% interval 0.83 to 1.01.
Homologues: Orthologues: chimpanzee MFSD13A (99% identical), macaque MFSD13A (98% identical), rabbit MFSD13A (92% identical), pig MFSD13A (92% identical), dog MFSD13A (91% identical), guinea pig MFSD13A (90% identical), rat Mfsd13a (90% identical), mouse Mfsd13a (89% identical), tropical clawed frog mfsd13a (68% identical), zebrafish mfsd13a (67% identical).
Diseases named in the same sentence as SLC68A1 in open-access papers:
SLC68A1 is named in the same sentence as 12 diseases in open-access papers, as found by Europe PMC text mining. Sharing a sentence is not in itself a finding about the gene and the disease.
SLC68A1 shares sentences with these, for which no sentence is quoted: colorectal cancer (8 papers); cancer (4); tumor (4); pancreatic cancer (3); schizophrenia (3); asthma (1); colon cancer (1); glioblastoma (1); hepatocellular carcinoma (1); leprosy (1); lung carcinoma (1); psychiatric disorder (1).